SALRNA1 (senescence associated long non-coding RNA 1)
Synonyms: SAL-RNA1; XLOC_023166
Gene: Long non-coding RNA gene on chromosome 14 (60,639,216 to 60,642,589, forward strand). Ensembl gene ENSG00000258952.
Diseases named in the same sentence as SALRNA1 in open-access papers:
SALRNA1 is named in the same sentence as 3 diseases in open-access papers, as found by Europe PMC text mining. Sharing a sentence is not in itself a finding about the gene and the disease. The quoted sentences say what the papers report.
cancer (1 paper, 2021). A tumor composed of atypical neoplastic, often pleomorphic cells that invade other tissues. "HHIPL2, XPO1, SALRNA1, ZBTB45, ANP32AP1, ACTR3BP5, LOC100129138, GPR45, and CAB39L gene deletions were associated with non-cancer subjects without FCH (p < 0.05), while RAB9BP1, LOC101928523, and MALRD1 gene deletions were related to non-cancer patients with FCH (p < 0.05)." (PMID 33431054, 2021).
SALRNA1 also shares sentences with these, for which no sentence is quoted: Alzheimer disease (1 paper); Hyperglycemia (1).